TNF (tumor necrosis factor)
Diseases named in the same sentence as TNF in open-access papers (continued):
Sharing a sentence is not in itself a finding about the gene and the disease.
Insulin resistance (continued). "The purpose of this study was to develop insulin resistance (IR) model on primary human tenocytes (hTeno) culture with tumour necrosis factor-alpha (TNF-α) treatment to study tenocytes homeostasis as an implication for diabetic tendinopathy." (PMID 32587790, 2020). "Our previous study reported that 4-HIL ameliorated insulin resistance state in HepG2 cells and 3 T3-L1 adipocytes via decreasing TNF-α and TACE." (PMID 33298044, 2020). "It was shown that insulin resistance can be modeled by treating fully differentiated adipocytes with TNF-α." (PMID 32024237, 2020). "Previous research has shown that adiponectin and adipokines (IL-6, TNF-α, and leptin) are related to a low vitamin D status and insulin resistance." (PMID 32659891, 2020). "Both IL-6 and TNF-α promote insulin resistance inhibiting lipoprotein lipase (LPL), decreasing triglyceride hydrolysis into free fatty acids, and increasing triglyceride storage in adipocytes, resulting in larger fat cells." (PMID 33643281, 2020). "The adipokine profile is drastically altered in insulin resistance, with increased secretion of inflammatory adipokines, such as tumor necrosis factor α (TNFα), and decreased secretion of insulin-sensitizing adipokines, such as adiponectin." (PMID 32041341, 2020). "We previously reported that 4-HIL potentiates anti-inflammatory and anti-insulin resistance effects through down-regulation of TNF-α and TNF-α converting enzyme (TACE) in 3 T3-L1 adipocytes and HepG2 cells." (PMID 33298044, 2020). "TNF-α leads to insulin resistance by means of phosphorylation of serine residues of the insulin receptor substrate-1, preventing the receptor substrate from binding to the insulin receptor, and inhibiting insulin action." (PMID 32947869, 2020). "In 1993, a link was found between increased levels of pro-inflammatory cytokines and tumor necrosis factor-alpha (TNF-α) produced by adipose tissue with insulin resistance." (PMID 33066473, 2020). "During insulin resistance, the production of IL-6 and TNF-α is increased in fat cells and they contribute to intra-abdominal excess fat." (PMID 32120970, 2020). "TNFα secretion by ATMs particularly influences the development of the MS as shown by the failure of TNFα−/− mice to develop diabetes and insulin resistance (IR)." (PMID 33240272, 2020). "The improvement of insulin action can be attributed to the effects of HO-1 attenuating the expression of insulin resistance mediators including TNF-α, IL-1β and increasing the levels of adiponectin." (PMID 32903449, 2020). "MTPα knockdown enhanced TNF-α-induced insulin resistance, as evidenced by significantly decreased insulin-stimulated glucose uptake in TNF-α-treated 3T3-L1 adipocytes (p < 0.0001)." (PMID 33009367, 2020). "TNF is an important cytokine in chronic inflammation, which influences lipid metabolism, the function of the endothelial cells and insulin resistance." (PMID 33327502, 2020). "Activation of hepatic JNK decreased the expression of PPARα target genes and FGF21, up-regulated cytokines such as TNFα and interleukin-1 (IL-1), and promoted insulin resistance in liver." (PMID 32850884, 2020). "Hyperglycemia is accompanied by an up-regulated expression of TNF-α, interleukin (IL)-1β, IL-6, and IL-18, which contribute to insulin resistance by both JNK and the IKKβ/NF-kβ pathway." (PMID 32431669, 2020). "For example, the expression of ADPN is suppressed when insulin resistance-inducing factors, such as TNFα, increase." (PMID 31945100, 2020). "In contrast, high adrenomedullin levels stimulated interleukin-6 and remarkably potentiated stimulatory effects of tumor necrosis factor-α, interleukin-1β and lipopolysaccharide that contribute to the development of insulin resistance." (PMID 33066780, 2020). "TNF-α enhances insulin resistance, supresseses the expression of adipokine, and increases free fatty acid concentration." (PMID 32598403, 2020).
Insulin resistance (continued). "In the present study, the administration of nicotinamide/streptozotocin resulted in an insulin resistance and an increase in the rate of IL-1β and TNF-α, confirming their involvement in the pathogenesis of type II diabetes." (PMID 33293987, 2020). "A potential role of TNF-α has been reported in the pathogenesis of insulin resistance and type 2 diabetes." (PMID 33293987, 2020). "LPS is the activator of pro-inflammatory cytokines, such as TNF-α, IL-1β, and IL-6, contributing to the development of insulin resistance." (PMID 33329010, 2020). "TNF-α, as another proinflammatory cytokine, has been generally identified as an important factor for the maintenance of insulin resistance, and recent studies also detect higher TNF-α concentrations in placentas and amniotic fluid of women with GDM." (PMID 33126577, 2020). "It is suggested that NF-κB can promote the development of GDM through interacting with TNF-α, leading to an increased insulin resistance in GDM." (PMID 33123597, 2020). "Similar outcomes have been observed in prediabetic mice, in which long-term exposure to high-fat diet and insulin resistance increases TNF-α protein in the hippocampus." (PMID 31992349, 2020). "Co-administering Lactobacillus paracasei N1115 and fructooligosaccharides in HFD-induced NAFLD mice reduced the levels of TNFα, insulin resistance and slowed the progression of cirrhosis." (PMID 32850884, 2020). "TNF-α plays an important role in inducing obesity-related insulin resistance, which is an important mechanism of metabolic syndrome." (PMID 33066473, 2020). "It plays a major role in the inhibition of insulin resistance via reduced TNFα and SOCS3 signaling and increased IGFBP-3 levels, resulting in REC protection from hyperglycemia-induced apoptosis." (PMID 32351607, 2020). "Hotamisligil, G et.al firstly showed that the proinflammatory cytokine TNF-α was able to induce insulin resistance." (PMID 32028957, 2020). "Studies in humans indicate reduced secretion of TNFα in adipose tissue in subjects with high adiponectin mRNA, whereas growing insulin resistance and increased body fat mass upregulate the expression of TNFα resulting in reduced adiponectin levels." (PMID 32443588, 2020). "IL-10 increases the glucose uptake, improves the insulin sensitivity and inhibits the TNF-α mediated insulin resistance in adipocytes and skeletal muscle with lowering glycaemia." (PMID 32824505, 2020). "The interaction between ox-LDL and Toll-like receptor 4 (TLR4) activates NF-κB path way resulting in elevated expression of pro-inflammatory cytokines including IL-1β, IL-6, and TNF-α which induce insulin resistance." (PMID 32005271, 2020). "Actually, TNF-α-mediated phenotypic shift of monocytes/macrophages in the adipose tissue is a central element of metabolic inflammation and insulin resistance in obese mice." (PMID 33033337, 2020). "TNF-alpha is a key factor in the development of NAFLD and NASH in both humans and animals and a relationship between TNF-alpha expression and insulin resistance in NASH has been previously demonstrated." (PMID 33306695, 2020). "The results reflected a decrease in insulin resistance and inflammatory markers TNF-alpha (tumor necrosis factor-alpha) and IL-6 (interleukin-6) associated with it." (PMID 33457118, 2020). "Similar results were seen in vivo, with MS-275 treatment of HF/HFr-fed mice ameliorating insulin resistance and reducing the expression of stress markers and TNF-α in skeletal muscle." (PMID 33362555, 2020). "In particular, a dose-response relationship between severity of periodontitis and plasma levels of TNFα, a cytokine known to promote insulin resistance, was found in adults with type 2 diabetes mellitus." (PMID 32486269, 2020). "In animal models and in obese humans, circulating TNF-α and TNF-α gene expression in adipose tissue were increased and associated with insulin resistance." (PMID 33233515, 2020).
Insulin resistance (continued). "Proinflammatory cytokines such as TNF-α and IL-1β exacerbate insulin resistance, while anti-inflammatory cytokines such as IL-4 and IL-10 promote insulin sensitivity." (PMID 32604889, 2020). "Overexpression of TNF-α is considered a hallmark of NAFLD-related inflammation; meanwhile, it is also associated with insulin resistance." (PMID 33315911, 2020). "Curcumin treatment also significantly increased cytokine (TNF-α, interferon-β, and IL-1β) treated glucose-induced insulin resistance, glutathione levels and reduced NO production." (PMID 31906278, 2020). "Type 2 diabetes patients display elevated plasma ceramide levels, and ceramide accumulation contributes to insulin resistance through activation of inflammatory cytokines such as TNF-α." (PMID 33424845, 2020). "It has previously been shown that excessive concentrations of TNF-α induce insulin resistance in humans in vivo." (PMID 32393961, 2020). "TNFα enhances lipolysis, thereby increasing serum free fatty acids and in this way favouring the development of insulin resistance." (PMID 32443588, 2020). "ORX decreased skeletal muscle mass and induced insulin resistance, and it also elevated serum TNF-α concentrations, an indicator of systemic inflammation, in the present study." (PMID 33371279, 2020). "TNF-α blockade is also known to reduce insulin resistance and improve lipid profiles in individuals with chronic sustained inflammation." (PMID 32824387, 2020). "TNF-α and IL-6 are considered to be contributors to insulin resistance and diabetes mellitus development." (PMID 32015418, 2020). "Quercetin-treated female Wistar rats showed decreased levels of IL-1β, IL-6, and tumor necrosis factor (TNF)- α, and decreased insulin resistance." (PMID 32903374, 2020). "TNF-α is mainly distributed on the surface of vascular endothelial cells, which can directly affect islet cells and lead to insulin resistance." (PMID 32280713, 2020). "The high degree of similarity between the cellular proteome at 4D and 8D further suggests that TNFα promotes sustained changes in protein regulation after the insulin resistance phenotype is developed." (PMID 33257747, 2020). "In a study, the expression of SIRT1 is reduced in myotubes and skeletal muscle isolated from T2D patients, who suggested the down-regulation of SIRT1 related to insulin resistance evoked by TNF-α in skeletal muscle." (PMID 32815547, 2020). "In another study, the treatment of primary myotubes with TNFα produced insulin resistance dependent on the elevated activity of p38 MAPK." (PMID 32899870, 2020). "What is more, obese adipose tissue contributes to the elevation of inflammatory cytokines, such as tumor necrosis factor α (TNFα) or interleukin-6 (Il-6), leading to chronic inflammation state promoting insulin resistance and cancer development." (PMID 32640537, 2020). "APS suppressed miR-721 expression to attenuate TNF-α-induced insulin resistance in 3T3-L1 adipocytes." (PMID 31894851, 2020). "Some studies suggest that TNF-α and IL-6 interact to interfere with insulin signal transduction, which leads to insulin resistance and eventually to the occurrence of GDM." (PMID 32280713, 2020). "For instance, both TNFα and IL-6 induce insulin resistance in rodents and block insulin action in murine (3T3-L1) adipocytes." (PMID 32397353, 2020). "First, we treated 3T3-L1 adipocytes with TNF-α (4 ng/ml) to create an insulin resistance (IR) model." (PMID 33009367, 2020). "The data from biochemical analysis showed that polydatin significantly decreased serum concentrations of insulin, TG, IL‐1β and TNF‐α, and alleviated insulin resistance in OGTT and ITT in fructose‐fed rats." (PMID 33058500, 2020). "In previous studies, lamin A/C has been shown to mediate the activation of adipose tissue macrophage inflammation by regulating the proinflammatory factors, such as NF-κB, or TNFα, contributing to the development of insulin resistance." (PMID 32012908, 2020).
Insulin resistance (continued). "Enhanced DUSP9 expression has a protective effect against the development of insulin resistance by counteracting the effects of proinflammatory cytokines, such as TNF-α." (PMID 33192474, 2020). "Levels of IL-1β, TNF-α, ROS and glucose consumption were performed to evaluate the severity of insulin resistance in FFA-induced L02 hepatocyte." (PMID 33308192, 2020). "While HFD-induced reduction in adiponectin was significantly improved by GML supplementation, the sensitivity of another adipocytokine, leptin, was also modulated, which induced hepatic expression of TNF-α and insulin resistance." (PMID 32265324, 2020). "TNF not only induces insulin resistance by direct interference with the insulin signaling but also by lowering adiponectin." (PMID 31912874, 2020). "The multiple linear regression models found that the behavioral variables, BF%, insulin resistance, and hs-CRP were linearly associated with the inflammatory biomarkers TNF-α, IL-6, and leptin." (PMID 32694929, 2020). "Even though LPS-induced steatosis is characterized by hepatic insulin resistance and the higher expression of tumor necrosis factor-α, IL-1 and IL-6, similar to the high-fat diet model, there are also some features that distinguish it from common NAFLD models." (PMID 32284043, 2020). "Visceral fat releases greater amounts of damaging adipokines (TNFα), which can result in insulin resistance and inflammation." (PMID 32131495, 2020). "The critical role of TNFα in the development of NAFLD-related insulin resistance has been proved in animal and human studies, and its neutralization can substantially reduce hepatic steatosis in genetically obese (ob/ob) mice." (PMID 32397353, 2020). "Further, to validate the functional impacts of the rs35652124 TT genotype on insulin resistance and wound healing process, we have studied the transcriptional profile of IL-10, TNF-α, and IL-6 in the study cohort based on their genotype." (PMID 32879654, 2020). "Another mechanism involved in TNFα induction of insulin resistance in peripheral tissues is activation of nuclear factor-κB (NF-κB) and stimulation of the transcription of cytokines and adhesion molecules." (PMID 32443588, 2020). "It has been shown that proinflammatory macrophages accumulate in the adipose of obese mice, and that these cells are dominant sources of TNF-α, which promotes insulin resistance." (PMID 32180699, 2020). "TNF-α plays an important role in glucose and lipid metabolism, and is closely related to insulin resistance and GDM; moreover, it is positively correlated with body mass index." (PMID 32434530, 2020). "Reduced level of adiponectin and increased levels of interleukin-6 (IL-6), tumor necrosis factor-α (TNF-α), free fatty acids, and resistin can reduce insulin-mediated glucose uptake due to insulin resistance." (PMID 32047529, 2020). "Inflammatory cytokines, such as TNF-α, can be cytotoxic by themselves and induce insulin resistance and apoptosis." (PMID 33187321, 2020). "Low-grade systemic inflammation has been independently implicated in metabolic disorders, such as insulin resistance and T2DM, and is typically presented with elevated levels of pro-inflammatory cytokines (i.e. IL-6, TNF-α, and CRP)." (PMID 33028418, 2020). "The majority of diabetic patients in the current study have BMI above 30, and their elevated TNF-α levels showed a significant positive correlation with insulin resistance." (PMID 32089876, 2020). "The influence of TNF-α on the development of insulin resistance has been confirmed both, in cell culture studies and animal studies." (PMID 33322719, 2020). "Among the various proinflammatory cytokines, TNF-α is one of the most important proinflammatory cytokines, which promotes the development of insulin resistance and T2DM." (PMID 33299532, 2020). "Another possible modulator of inflammation in GDM is insulin resistance, which is linked to increased levels of hs-CRP, IL-6, and TNF-α." (PMID 33081175, 2020).
Insulin resistance (continued). "Mangiferin has also been shown to exert a antihypoglycemic effect by modulating glucose metabolism, ameliorating insulin resistance, lowering cholesterol synthesis, and inhibiting the expression of the TNF-α." (PMID 32076626, 2020). "TNFα inhibits PPARγ activity and consequently leads to suppression of adipocyte differentiation and several conditions including insulin resistance." (PMID 32524217, 2020). "As with IL-6, TNFα levels positively correlate with adiposity, BMI, insulin levels, and insulin resistance." (PMID 32158768, 2020). "Excessive TNF-α can lead to the breakdown of fat particles in fat cells, resulting in an increase of free fatty acid content, which eventually leads to insulin resistance." (PMID 32952498, 2020). "Tumor necrosis factor and free fatty acids are involved in the development of insulin resistance, and then the activation of PPARγ contributed toward down-regulation of both parameter and increased the insulin sensitivity." (PMID 32815547, 2020). "Depletion of hepatic macrophages can protect against insulin resistance, where TNF-α serves as an important mediator of this effect." (PMID 32121028, 2020). "In obese rodents and humans, the expression of TNF-α is reportedly increased and is correlated with insulin resistance and adiposity." (PMID 32153977, 2020). "Type 1 diabetes is characterized by the presence of hyperglycemia together with insulin resistance, oxidative stress as well as elevated production of cytokines, such as C-reactive protein, interleukin (IL)-6 and tumor necrosis factor (TNF)-α7." (PMID 32404878, 2020). "In adipocytes and peripheral tissue, the high level of TNF-α from the macrophages of tissues induces insulin resistance by altering insulin signalling via serine phosphorylation, again, leading to the development of T2DM." (PMID 33299532, 2020). "To gain an insight on the dynamic effects of TNFα-induced insulin resistance, we performed a time-resolved proteomic analysis, at 4 days (4D) and 8 days (8D) of chronic treatment." (PMID 33257747, 2020). "Several in vitro studies have revealed a secondary mechanism linking the adipokine, TNF-α, to insulin resistance by regulating ceramide synthesis." (PMID 32903449, 2020). "TNF-α can hinder insulin signaling by inducing the expression of signal transduction inhibitor 3, leading to insulin resistance (IR)." (PMID 33708118, 2020). "Previous reports have suggested that chronic TNFα treatment for a period of 4 days is sufficient to induce insulin resistance in both myocytes and murine adipocytes." (PMID 33257747, 2020). "Previous studies found that the TLR-4-LPS pathway can stimulate pro-inflammatory cytokines in the skeletal muscle, and pro-inflammatory cytokines, such as TNF-α, promote insulin resistance though NF-kB inflammatory signaling." (PMID 33019697, 2020). "These drastic differences in the proteome of TNFα treated adipocytes are likely due to the development of insulin resistance, which is achieved after 4 days of continuous TNFα exposure." (PMID 33257747, 2020). "In diabetes, the accumulation of activated innate immune cells leads to the release of inflammatory mediators, especially, IL-1β and TNFα, which stimulates insulin resistance and β-cell damage." (PMID 33083287, 2020). "In particular, IL-6 and TNFα seem to directly interfere with the normal transmission of insulin signals, promoting the onset of insulin resistance and later the onset of type 2 diabetes." (PMID 33330284, 2020). "Administration of neferine (5 mg/kg) for 3 weeks via gastrogavage has been reported to decrease fasting blood glucose, insulin, TG, and TNF-α and increase insulin sensitivity in insulin resistance-induced rats." (PMID 33266423, 2020). "NF-κB can interact with tumour necrosis factor alpha (TNF-α) to form a positive feedback loop of low-grade inflammation and increase insulin resistance in GDM and thus promote the development of GDM." (PMID 33123597, 2020).